KLF10 (KLF transcription factor 10)
Diseases named in the same sentence as KLF10 in open-access papers (continued):
Sharing a sentence is not in itself a finding about the gene and the disease.
hypertrophic cardiomyopathy (2 papers, 2020 to 2022). "A study by the Spelsberg group revealed a positive correlation between six missense mutations in KLF10 and hypertrophic cardiomyopathy." (PMID 33396939, 2020).
liver cancer (2 papers, 2023). An epithelial or non-epithelial malignant neoplasm that arises from the liver. "The results of this study suggest that loss of KLF10 facilitates liver cancer development with alteration in TGFβ signaling." (PMID 37946098, 2023). "In addition, KLF10-depleted liver cancer cells and HSCs demonstrated increased invasiveness." (PMID 37946098, 2023).
liver cirrhosis (2 papers, 2012 to 2018). "Both KLF9 (1.7-fold, p = 0.038) and KLF10 (1.73-fold, p = 0.030) were found to be significantly higher expressed in liver cirrhosis tissue from ZZ compared to MM AAT." (PMID 22621770, 2012). "Furthermore, KLF10 plays a role in hyperglycemia, human chronic obstructive pulmonary diseases and liver cirrhosis, tendon repair, and hypoxia." (PMID 29799499, 2018). "The higher expression of KLF 9 and KLF10 has been verified in the replication cohort with AATD-related end-stage lung emphysema and liver cirrhosis." (PMID 22621770, 2012). "Further conformation in a different cohort of end-stage COPD lungs and in liver cirrhosis tissues showing that SNAI1, KLF9 and KLF10 are higher expressed in ZZ relative to MM AAT subjects, allows us to propose that the increased expression of zinc finger transcription factors is related to AATD." (PMID 22621770, 2012).
liver disease (2 papers, 2020 to 2023). "In the present study, we investigated the role of KLF10 in the progression of liver disease upon a high-sucrose diet (HSD) in mice." (PMID 33396939, 2020). "Krüppel-like factor 10 (KLF10) is involved in a positive feedback loop that regulates transforming growth factor β (TGFβ) signaling, and TGFβ plays an important role in the pathogenesis of liver disease." (PMID 37946098, 2023).
lung adenocarcinoma (2 papers, 2018 to 2023). A carcinoma that arises from the lung and is characterized by the presence of malignant glandular epithelial cells. "Because E74-like ETS transcription factor 3 (ELF3) was reported to bind to Notch-3 gene promoter with transcription regulation in K-RAS-mediated lung adenocarcinoma, we evaluated the interaction of KLF10 and ELF3 in Panc-1 cells." (PMID 37308977, 2023).
non-small cell lung carcinoma (2 papers, 2021 to 2022). A group of at least three distinct histological types of lung cancer, including non-small cell squamous cell carcinoma, adenocarcinoma, and large cell carcinoma. "Previous studies of Vivek Kumar Mishra found that in non-small cell lung cancer, KLF10 suppresses TGF-β-induced EMT via a negative feedback mechanism." (PMID 35668494, 2022).
Nonalcoholic Fatty Liver Disease (2 papers, 2014 to 2021). "A recent study reports that KLF10 can also suppress lipogenic genes and that glucose stimulation induces KLF10 mRNA expression, suggesting the possible role of KLF10 on glucose and lipid metabolism, two important pathways in relation to nonalcoholic fatty liver disease." (PMID 24986741, 2014).
Sepsis (2 papers, 2012 to 2018). Sepsis is defined as life-threatening organ dysfunction caused by a dysregulated host response to infection. "Transcriptional regulators like PLAGL2, EBF1, TCF7, KLF10 and SBNO2, previously not described in sepsis, are differentially expressed at early and late time points." (PMID 23009705, 2012).
Age-related cataract (1 paper, 2024). A type of cataract (opacification of the lens) that forms during the course of aging. "The T allele of rs13053109 in the promoter region of CRYAA is associated with increased risk of age-related cataracts and shows increased binding by KLF10 with consequent decrease in CRYAA transcription, providing indirect support for the role of the NFE2L2 pathway in age-related cataractogenesis." (PMID 39594457, 2024).
Atrophy (1 paper, 2025). Any weakening or degeneration, especially through lack of use. "KLF5 and KLF10 are key mediators of early muscle atrophy, whereas FOS increases after denervation‐induced muscle atrophy." (PMID 39435630, 2025).
Beta-thalassaemia (1 paper, 2024). "Indeed, Sin3A is known to worsen Beta-thalassaemia severity, possibly inhibiting the action of KLF10 which is known to ameliorate symptoms in a range of Beta-Haemoglobinopathies32." (PMID 38862545, 2024).
Cerebral ischemia (1 paper, 2023). Restriction of arterial blood supply to the brain associated with insufficient oxygenation to support the metabolic requirements of the tissue. "In cerebral ischemia-reperfusion injury, down-regulation of KLF10 can inhibit N-myc/PTEN signaling pathway and promote the proliferation and repair of brain nerve cells." (PMID 36878898, 2023).
cervical squamous cell carcinoma (1 paper, 2018). A squamous cell carcinoma arising from the cervical epithelium. "The SiHa cell line was chosen as an experimental model for KLF10 knock down because this cell line was established from a cervical squamous cell carcinoma that contains HPV16 sequences, most of CC cases have similar parameters." (PMID 29930344, 2018).
cholangiocarcinoma (1 paper, 2021). A carcinoma that arises from the intrahepatic biliary tree (intrahepatic cholangiocarcinoma) or from the junction, or adjacent to the junction, of the right and left hepatic ducts (hilar cholangiocarcinoma). "According to TCGA- CHOL data, KLF10 expression was significantly downregulated in cholangiocarcinoma tissues." (PMID 34805140, 2021). "Under PDT treatment, EGFR overexpression and KLF10 silencing attenuated the anti-cancer effects of PDT on gemcitabine-resistant cholangiocarcinoma cells by promoting cell viability, inhibiting apoptosis, and increasing S phase cell proportion." (PMID 34805140, 2021). "The KLF10/EGFR axis participates in the process of the inhibition of PDT on gemcitabine-resistant cholangiocarcinoma cells." (PMID 34805140, 2021). "The KLF10/EGFR axis participates in the process of the inhibition of PDT on gemcitabine-resistant cholangiocarcinoma cells growth." (PMID 34805140, 2021). "Among the 20 upregulated transcription factors, CEBPD, CSRNP1, and KLF10 were regularly underexpressed in cholangiocarcinoma but upregulated by PDT treatment." (PMID 34805140, 2021). "As speculated, KLF10 silencing or EGFR overexpression attenuated the anti-cancer effects of PDT on gemcitabine-resistant cholangiocarcinoma cells by increasing S phase cell proportion, promoting cell viability, and inhibiting cell apoptosis." (PMID 34805140, 2021). "Moreover, also according to TCGA-CHOL data, cholangiocarcinoma patients with lower KLF10 expression predicted poorer overall survival, disease-specific survival, and progression-free survival." (PMID 34805140, 2021). "Within cholangiocarcinoma, KLF10 could be regulated by miR-106b and might participate in the anti-apoptotic effects of miR-106b on cholangiocarcinoma cells." (PMID 34805140, 2021). "To investigate whether the KLF10/EGFR axis plays a dynamic role in the process of PDT reversing cholangiocarcinoma gemcitabine resistance, we co-transfected RBE-R cells with si-KLF10 and si-EGFR, exposed the cells to PDT treatment, and examined for the mRNA expression of KLF10 and EGFR." (PMID 34805140, 2021). "Thus, KLF10 might be involved in the inhibition of PDT on gemcitabine-resistant cholangiocarcinoma cells." (PMID 34805140, 2021). "Thus, KLF10 might participate in the process of PDT reversing cholangiocarcinoma gemcitabine resistance." (PMID 34805140, 2021). "After confirming KLF10 negative regulation of EGFR, next, the specific effects of these two factors on the process of PDT reversing cholangiocarcinoma gemcitabine resistance were investigated." (PMID 34805140, 2021). "More importantly, when co-transfected to gemcitabine-resistant cholangiocarcinoma cells, the effects of si-KLF10 were significantly reversed by EGFR silencing, indicating that KLF10 participates in the inhibition of PDT on gemcitabine-resistant cholangiocarcinoma cells through EGFR." (PMID 34805140, 2021). "KLF10 and EGFR might be involved in the process of PDT reversing cholangiocarcinoma gemcitabine resistance." (PMID 34805140, 2021).
chronic lung disease (1 paper, 2025). According to the definitions of the American and British Thoracic Societies, including pulmonary functional tests, X-rays, and CT scans for items such as fibrosis, bronchiectasis, bullae, emphysema, nodular or lymphomatous abnormalities. "KLF10 attenuates pulmonary inflammation by suppressing NPRA expression, playing a critical role in chronic lung disease pathogenesis." (PMID 41105618, 2025).
Cirrhosis (1 paper, 2022). A chronic disorder of the liver in which liver tissue becomes scarred and is partially replaced by regenerative nodules and fibrotic tissue resulting in loss of liver function. "While cirrhosis has not been observed in Klf10 KO mice under standard conditions, it should be noted that hepatic expression of Klf10 is increased in fatty liver of obese mice and involved in several mechanisms which are dysregulated in NAFLD (Non-alcoholic fatty liver diseases)." (PMID 36507464, 2022).
delirium (1 paper, 2025). A disorder characterized by confusion; inattentiveness; disorientation; illusions; hallucinations; agitation; and in some instances autonomic nervous system overactivity. "Novel associations with delirium included transcripts related to stress granule assembly and the T cell regulators DUSP2 and KLF10." (PMID 40982210, 2025).
heart arrhythmia (1 paper, 2019). "Five genes (PRKCG, EREG, BHLHE40, KLF10, and NAMPT) targeted by AA-miRNAs may contribute to the pathogenesis of heart arrhythmia such as AF." (PMID 31607954, 2019).
heart failure (1 paper, 2024). Inability of the heart to pump blood at an adequate rate to meet tissue metabolic requirements. "Notably, several transcription factors highlighted by our approach, such as FOXC1 in heart failure and KLF10 and KLF15 in ischemic cardiomyopathy, are supported by existing literature, validating our approach." (PMID 38673810, 2024).
kidney damage (1 paper, 2022). "Under diabetic conditions, KLF10 induces KDM6A expression, causing proteinuria and irreversible kidney damage." (PMID 36012674, 2022).
lipid metabolism disorder (1 paper, 2021). "Moreover, KLF10-silenced groups exhibited overexpression of Cyb5r3, Fads1, and Fads2, which are involved in diseases such as lipid metabolism disorder." (PMID 34869587, 2021).
lymphoma (1 paper, 2015). A malignant (clonal) proliferation of B- lymphocytes or T- lymphocytes which involves the lymph nodes, bone marrow and/or extranodal sites. "The KLF10-TGFβ-SMAD pathway has been implicated in the development of several other human cancers including those of the prostate, pancreas, kidney, lymphoma, and brain." (PMID 26807442, 2015).
myocardial infarction (1 paper, 2024). Gross necrosis of the myocardium, as a result of interruption of the blood supply to the area, as in coronary thrombosis. "KLF10 KO mice with myocardial infarction showed better cardiac function and smaller scar areas than C57BL/6J mice." (PMID 38279278, 2024).
papilloma (1 paper, 2022). A benign epithelial neoplasm that projects above the surrounding epithelial surface and consists of villous or arborescent outgrowths of fibrovascular stroma. "In mice, KLF10 knockout facilitates skin tumorigenesis and papilloma formation in response to DMBA/TPA treatment." (PMID 35743973, 2022).
Peri-Implantitis (1 paper, 2022). An inflammatory process with loss of supporting bone in the tissues surrounding functioning DENTAL IMPLANTS. "GSE178351 dataset (involving four peri-implantitis patients and three healthy people) dataset and GSE156993 dataset (involving five poorly controlled T2DM with periodontitis and six healthy individuals) were used to analyze the expression level of KLF10." (PMID 35730406, 2022).
periodontitis (1 paper, 2022). An acute or chronic inflammatory process that affects the tissues that surround and support the teeth. "GSE178351 dataset and GSE156993 dataset were utilized to explore the expression of KLF10 in periodontitis." (PMID 35730406, 2022).
pneumonia (1 paper, 2025). An acute, acute and chronic, or chronic inflammation focally or diffusely affecting the lung parenchyma, caused by an infection in one or both of the lungs (by bacteria, viruses, fungi, or mycoplasma.). "Similarly, our findings demonstrate that circ_0001239 interacts with YTHDC2, thereby disrupting KLF10 mRNA stability and exacerbating pneumonia-associated lung injury." (PMID 41105618, 2025). "To summarize, our study unveils that METTL3 upregulates circ_0001239 expression via m6A modification, increases the binding of circ_0001239 to YTHDC2, and inhibits KLF10 expression, ultimately worsening lung injury in neonatal mice with Spn-induced pneumonia." (PMID 41105618, 2025). "Circ_0001239 overexpression or KLF10 knockdown reversed the protective effects of low expression of METTL3 on lung damage in neonatal mice with pneumonia." (PMID 41105618, 2025). "In conclusion, METTL3 aggravates Spn-induced lung injury via m6A-dependent circ_0001239/YTHDC2/KLF10 axis, thereby providing potential therapeutic targets for severe pneumonia." (PMID 41105618, 2025). "Additionally, the upstream regulatory mechanisms of METTL3 and downstream regulatory mechanisms of KLF10 should be further investigated, which may lead to the identification of new therapeutic approaches for pneumonia intervention." (PMID 41105618, 2025). "Our experiment aligns with this observation, demonstrating that circ_0001239/YTHDC2-mediated KLF10 upregulation alleviates Spn-induced lung injury, whereas KLF10 downregulation diminishes the protective effect of METTL3 knockdown in neonatal mice with Spn-induced pneumonia." (PMID 41105618, 2025).
prostate carcinoma (1 paper, 2020). A carcinoma that arises from epithelial cells of the prostate gland. "So far the role of KLF10 in humans has been only investigated in pancreatic, breast and prostate cancer cells where it has been described to inhibit proliferation and to induce apoptosis thus having a potential tumor suppressor function." (PMID 32699233, 2020).
pulmonary fibrosis (1 paper, 2020). Chronic progressive interstitial lung disorder characterized by the replacement of the lung tissue by connective tissue, leading to progressive dyspnea, respiratory failure, or right heart failure. "Although the roles of KLF10 in regulating the cellular physiology of pulmonary fibroblasts remain largely unknown, the curcumin-induced upregulation of KLF10 might provide potential targets to reverse pulmonary fibrosis, and therefore deserve further study." (PMID 33233354, 2020).
rheumatoid arthritis (1 paper, 2022). A chronic, systemic autoimmune disorder characterized by inflammation in the synovial membranes and articular surfaces. "RT-qPCR and Western blot detected the expressions of PDLIM2 and KLF10 in Human Rheumatoid arthritis FLSs (HFLSs-RA)." (PMID 34713769, 2022).
tumor (50 papers, 2003 to 2025). "Upregulating KLF10 and/or suppressing Notch signaling, genetically or pharmacologically, delayed tumor growth of PDAC with KLF10 deficiency." (PMID 37308977, 2023). "Genetically depleting Notch-3/4, or pharmacologically suppressing Notch signal by γ-secretase inhibitor ameliorated the stem cell phenotypes and tumor growth induced by KLF10 deficiency in PDAC cells." (PMID 37308977, 2023). "In this study, IHC staining demonstrated that the loss of KLF10 was associated with advanced tumor stages and short survival." (PMID 35743973, 2022). "KLF10 was involved in cell proliferation and apoptosis, and its levels were inversely associated with BC stages, implying that it had a tumor suppressor function." (PMID 34830241, 2021). "In the parameter of T value, a high KLF10 expression was associated with a higher 5-year survival rate in the T1 subgroup (with a tumor smaller than 2 cm)." (PMID 33379261, 2020). "This novel KLF10/SIRT6 signaling pathway presents promising therapeutic potential by ameliorating tumor metastasis through the coordinated regulation of metabolic and migratory processes." (PMID 39682281, 2024). "KLF10, upregulated by RT, acts as a tumour suppressor gene in several cancers through the TGF-β signalling pathway." (PMID 39202425, 2024). "One significant pathway involves the interaction between SIRT6 and Krüppel-like factor 10 (KLF10), a known tumor suppressor." (PMID 39682281, 2024). "KLF10, deficient in two-thirds of 105 patients with resected pancreatic PDAC, was associated with rapid local recurrence and large tumor size." (PMID 37308977, 2023). "Conditional overexpressing KLF10 in MiaPaCa and stably depleting KLF10 in Panc-1 (Panc-1-pLKO-shKLF10) cells were established for evaluating sphere formation, stem cell markers expression and tumor growth." (PMID 37308977, 2023). "Many studies have demonstrated the tumor suppressor function of KLF10 in terms of cell proliferation inhibition and apoptosis induction." (PMID 37958386, 2023). "Reduced KLF10 expression was noted in the tumor tissues of PDAC patients compared with normal pancreas tissue in immunohistochemistry (IHC) studies." (PMID 37308977, 2023). "The consensus is that high KLF10 expression is not only significantly correlated with better overall survival and lower tumor stages but can also be used to predict treatment efficacy for formulating therapeutic interventions in PDAC." (PMID 37239940, 2023). "We used metformin, DAPT, and evodiamine in the murine tumor model to demonstrate that KLF10, the Notch signaling pathway and Notch-3 are potential therapeutic targets in PDAC with KLF10 deficiency." (PMID 37308977, 2023). "Although our results did not reveal a significant effect of KLF10 deletion on liver fibrogenesis, the loss of KLF10 led to increased incidence of DEN-induced HCC in mouse liver, suggesting that KLF10 has a tumor suppressor role." (PMID 37946098, 2023). "Tumor specimens of PDAC patients were immune-stained of KLF10 to correlate with local recurrence after curative resection." (PMID 37308977, 2023). "RAF-1 phosphorylation and PIN1 isomerization coordinately regulate KLF10 stability and tumor progression." (PMID 37958386, 2023). "When HCC was induced by DEN treatment, KLF10 deletion resulted in a significantly greater tumor burden compared with the burden in DEN-treated WT mice." (PMID 37946098, 2023). "Gene expression profiles of PDAC also showed reduced KLF10 transcripts of tumor tissue compared with normal pancreas tissue in several databases." (PMID 37308977, 2023). "KLF10 (Krüppel-like factor 10) has been established in several studies for its role as a tumor suppressor in cancer." (PMID 36755291, 2023). "Multiple studies in vitro and in vivo showed that ectopic expression of KLF10 led to increased apoptosis and delayed growth of orthotopic tumors, while Klf10 deletion led to aggressive tumor growth." (PMID 37239940, 2023).